ISG15 (ISG15 ubiquitin like modifier)
Diseases named in the same sentence as ISG15 in open-access papers (continued):
Sharing a sentence is not in itself a finding about the gene and the disease.
breast cancer (continued). "Indeed, high ISG15 levels correlate with poor overall survival in PDAC, and ISG15 levels have been related to tumorigenesis, tumor progression and metastasis in other malignancies such as prostate or breast cancer." (PMID 29373514, 2018). "Future studies of the immunomodulatory effects of free intracellular ISG15 in breast cancer cells might benefit from an in-depth examination of its effects on ISG15-mediated protein conjugation." (PMID 27626310, 2016). "In tissue culture experiments, the level of ISG15 expression in breast cancer cell lines was inversely proportional to the level of polyubiquitylated proteins (non-ISG ubiquitylation), and the siRNA-mediated knockdown of ISG15 increased the level of polyubiquitylation." (PMID 27626310, 2016). "Although their findings suggest that free ISG15 might be useful for augmenting treatments for breast cancer, how free ISG15 stimulated MHC class I expression in the xenografted cells was not entirely clear." (PMID 27626310, 2016). "Evidence of the role of ISG15-mediated conjugation of cytoskeletal proteins in breast cancer could explain the altered morphology of tumor cells, but it is unclear how cell division might be affected by ISGylation." (PMID 27626310, 2016). "Breast cancer cells stably expressing control, ISG15, and UbcH8 (ISG15-specific E2 ligase) shRNAs were used to assess the immunoregulatory and antitumor function of free ISG15 in cell culture (in vitro) and in nude mice (in vivo)." (PMID 25749047, 2015). "Because constitutive ISG15 induction confers a malignant phenotype on breast cancer cells, we anticipated that ZR/control shRNA cells overexpressing ISG15 would form large tumors compared to the ZR/ISG15 shRNA cells silenced for the ISG15 expression." (PMID 25749047, 2015). "To test the potential role of ISG15 in activating the adaptive arm of the immune system, we assessed MHC class I surface expression, a marker for efficient antigen presentation, on T47D breast cancer cells devoid of free ISG15 expression and IFNβ-treated T47D cells expressing high levels of ISG15." (PMID 25749047, 2015). "Together, results using two different antibodies directed against CD49b, and two different breast cancer xenografts implanted in two different colonies of nude mice demonstrate that ISG15 induces infiltration of NK cells, and inhibits tumor growth in nude mice." (PMID 25749047, 2015). "Indeed, ISG15 inhibits bulk polyubiquitylation and the subsequent 26S proteasome-mediated degradation of target proteins in breast cancer cells." (PMID 21298066, 2011). "For instance, the level of polyubiquitinated proteins is increased in response to ISG15 knockdown in ZR-75-1 breast cancer cells, which could result from a competition between ISG15 and ubiquitin for common E2 enzymes, such as UbcH8, and UbcH6." (PMID 22022510, 2011). "Significantly, ISG15 has been shown to be a prognostic marker for breast cancer." (PMID 21897875, 2011). "Enhanced expression of ISG15 in breast cancer was further validated by cDNA dot-blot analysis." (PMID 18627608, 2008). "We analysed the results particularly in correlation to clinicopathological data, such as hormone receptor status, HER2 status and patient survival data, in order to validate ISG15 as a new prognostic marker and potential drug target in the treatment of human breast cancer." (PMID 18627608, 2008). "Interestingly, upregulation of ISG15 was highly abundant in the breast cancer cell line MDA-MB231, a cell line shown to be highly metastatic in nude mouse models." (PMID 18627608, 2008). "Our analyses showed ISG15 overexpression in human breast carcinomas relative to normal breast tissue at the RNA and protein level indicating that ISG15 may represent a candidate oncogene in human breast cancer." (PMID 18627608, 2008).
breast cancer (continued). "ISG15 protein expression was analysed in two independent cohorts on tissue microarrays; in an initial evaluation set of 179 breast carcinomas and 51 normal breast tissues; and in a second large validation set of 646 breast carcinomas and 10 normal breast tissues." (PMID 18627608, 2008). "Overexpression of ISG15 protein in breast carcinomas could be confirmed by immunohistochemistry of a TMA." (PMID 18627608, 2008). "Furthermore, mammary tumors had higher levels of ISG15 mRNA and protein than normal mammary tissue, and ISG15 may regulate cytoskeleton reorganization." (PMID 36771004, 2023). "Moreover, an increase in the ubiquitination levels in breast cancer cells is promoted by the reduction of ISG15 or UBCH8 (ubiquitin‐conjugating enzyme H8, an ISG15 conjugating E2 enzyme), suggesting that ISGylation avoids protein ubiquitination and confers stability." (PMID 36071546, 2022). "Studies have also shown that treatment with exogenous ISG15 protein can reduce the burden of primary and metastatic breast cancer (BC) in mice." (PMID 32641707, 2020). "Various chemotherapeutic agents have been shown to increase, and ISG15 expression has been shown to be associated with tumor response to IFN-α treatment, chemotherapy, and radiotherapy, as well as the survival of patients with acute promyelocytic leukemia, ovarian cancer, or breast cancer." (PMID 27626310, 2016). "In addition, elevated expression of ISG15 suppresses camptothecin-induced proteasome-mediated degradation of topoisomerase I in breast cancer cells, further supporting the antagonistic role of ISG15 in ubiquitin-mediated degradation of many endogenous cellular proteins." (PMID 21298066, 2011). "Possibly due to a weak association with the ER status, ISG15 expression could not be identified as an independent prognostic factor in a multivariate analysis in this breast cancer cohort." (PMID 18627608, 2008). "The high levels of SUMO2, ISG15, NEDD8, and UBD are related to worse prognosis outcomes in breast cancer." (PMID 41583390, 2026). "Lastly, the expression of ISG15 affects DMFS in breast cancer, PFS in ovarian cancer, DFS in pancreatic cancer, PPS in breast cancer, gastric cancer, AML, and myeloma, as well as EFS in AML and myeloma." (PMID 40208307, 2025). "Elevated ISG15 mRNA and protein levels correlate with lymphovascular invasion (LVI), histological grade, tumor size, HER2-enriched breast cancer subtypes, immune markers (CD8, FOXP3, CD68), and poor prognosis." (PMID 40103488, 2025). "Obviously, proportions of ISG15+ macrophages and IFIT3+ neutrophils in primary tumor have low levels as that in normal lung but not TPPP3+ monocytes and IL12B+ DCs, which indicate that these myeloid subpopulations may have different degrees of association with breast cancer metastasis to lung." (PMID 37483625, 2023). "Both breast cancer and melanoma BrM cells enhanced the expression of IFIT1 and Ubiquitin Like Modifier (ISG15) in the cocultured astrocytes." (PMID 37149684, 2023). "Extracellular ISG15 has been shown to stimulate IFN-γ secretion by T and NK cells, while IFN-γ signaling components and the ISG15 gene are upregulated in breast cancer cells, implying a link between IFN-γ signaling and ISGylation." (PMID 38036512, 2023). "ISG15 and ISGylation induced by oncogenic Kirsten-Ras (Ki-Ras) suppress lysosomal degradation of Ki-Ras, which facilitates migration and EMT of breast cancer cells." (PMID 36319753, 2022). "ISG15 and ISGylation have been demonstrated to be involved in epithelial–mesenchymal transition (EMT), cell motility, invasion, and metastasis of breast cancer cells." (PMID 36319753, 2022). "This group reported that high levels of fibronectin-binding integrins and ISG15 promote the invasion of the malignant MDA-MB-231 breast cancer cells and correlate with poor survival rates in a large cohort of breast cancer patients." (PMID 35159348, 2022).
breast cancer (continued). "Consistent with this conclusion, ISG15 and UBCH8 (ISG15-specific conjugating enzyme) promote breast cancer cell migration by disrupting F-actin architecture and the formation of focal adhesions." (PMID 35159348, 2022). "UBA7/ISG15 signaling axis has been a prime focus in lung cancer, and many studies show downregulation of UBA7 in lung and breast cancer." (PMID 35612714, 2022). "Consistent with the model, free ISG15 inhibits tumor growth in vivo (current study), and vaccination against free ISG15 results in CD8-mediated reductions in both primary and metastatic mammary tumor burden in mice." (PMID 25749047, 2015). "Recently it has been pointed out that a disabled ISG15-pathway decreases the cellular sensitivity to chemotherapeutic agents camptothecin (CPT), as shown in breast cancer." (PMID 26506425, 2015). "Both free and conjugated forms of ISG15 are induced in IFNβ-treated T47D and MDA/LV-control shRNA breast cancer cells." (PMID 25749047, 2015). "Therefore, ISG15 may represent a novel breast tumour marker with prognostic significance and may be helpful in selecting patients for and predicting response to the treatment of human breast cancer." (PMID 18627608, 2008). "Moreover, STING expression was also positively correlated with the expression of the IFN‐I signaling genes ISG15, STAT1 and STAT2 in breast cancer MSCs." (PMID 38638003, 2024). "ISG15 has been shown to be involved in some subtypes of breast cancer, including TNBC, and UBE2L6/UBCH8, a ubiquitin conjugating E2 enzyme, has been reported to mediate ISG15 conjugation." (PMID 29350614, 2018). "Unlike the findings of studies of breast cancer, only free ISG15 was detected in bladder cancer tumors by western blotting, and immunohistochemistry showed that the majority of free ISG15 in tumor cells was located in the nucleus." (PMID 27626310, 2016). "Our results that MG132 blocks MHC-class I presentation thus suggest that increased MHC class I presentation in ISG15 overexpressing breast cancer cells is dependent on proteasome function but not the autophagy pathway." (PMID 25749047, 2015). "For example, among a panel of breast cancer cell lines, ISG15 is highly expressed in ZR-75-1 and MDA-MB-231, but not in BT-474 cells." (PMID 21897875, 2011). "In addition, the CD4+_ISG15, CD4+_MKI67 and IFN-I signatures identified in tumor-infiltrating CD4+ T cells showed enrichment in the same tissue region in a human breast cancer specimen subjected to spatial transcriptomic profiling (10x Visium)." (PMID 38383773, 2024). "In breast cancer models, ISG15 and/or ISGylation correlate with aggressive features such as, cell cycle progression, cell motility and tumour growth in xenograft models, yet, we still do not know if ISG15 is just a bystander or indeed a driver." (PMID 34556814, 2021). "Since MDA/LV-UbcH8 cells have free ISG15 but lack ISG15 conjugates, 30% more surface expression in UbcH8 shRNA cells suggest that free ISG15 rather than ISG conjugation to intracellular targets is required for increased antigen presentation in breast cancer cells." (PMID 25749047, 2015). "We show that extracellular free ISG15 suppresses breast tumor growth and increases NK cell infiltration into xenografted breast tumors in nude mice, and intracellular free ISG15 enhances major histocompatibility complex (MHC) class I surface expression in breast cancer cells." (PMID 25749047, 2015). "Furthermore, high mRNA and protein expression of ISG15 is associated with lymphovascular invasion (LVI), higher histological grade, larger tumor size, hormone receptor-negative, HER2-positive, and HER2-enriched breast cancer subtypes." (PMID 36771004, 2023).
influenza (39 papers, 2008 to 2025). An acute viral infection of the respiratory tract, occurring in isolated cases, in epidemics, or in pandemics; it is caused by serologically different strains of viruses (influenzaviruses) designated A, B, and C, has a 3-day incubation period, and usually lasts for 3 to 10 days. "The population data support the in vivo relevance of the mSTARR-seq data, while the mSTARR-seq data suggest that baseline variation in ISG15 methylation in vivo is causally meaningful to the response to influenza." (PMID 37293015, 2023). "In contrast, ISG15 deficient mice demonstrated to be more sensitive to influenza and herpes simplex virus infections." (PMID 30949318, 2019). "ISG15 knockout (ISG15−/−) mice show increased susceptibility to influenza, herpes, chikungunya (alphavirus), and sindbis virus infections as measured by decreased survival rates compared to wild type mice." (PMID 22666250, 2012). "Furthermore, this GO analysis indicated that genes associated with the antiviral response to influenza (e.g., Ifi27l2a, Isg20, Oas1a, Isg15, Ifit1, Oasl1, and Ifit3) were strongly enriched in mice vaccinated with WIV alone as compared with mice vaccinated with WT IL-1β or CD8α ALN-1." (PMID 32714571, 2020). "IFIT1, IFIT3, IFITM3, MX1, and ISG15 have all been shown to possess anti-influenza activities; however, a genetic variant of IFITM3 has been associated with severe influenza infection and higher hospitalization rate." (PMID 33347425, 2020). "These species-specific differences in ISG15 have been suggested to contribute to influenza B’s limited host tropism." (PMID 31869347, 2019). "Both ISG15 and the OAS-RNase L system have been shown to reduce susceptibility to influenza in experimental models." (PMID 26393920, 2015). "A number of those genes have been shown previously to play a protective role during the influenza infection (e.g. Isg20, Isg15, Gbp1, etc.)." (PMID 24073225, 2013). "One group of ISGs, as represented by several well-known anti-influenza ISGs (Gbp3, Ifit3, Isg15, and Mx1/2), showed a kinetic pattern of mRNA expression largely resembling that of IFN-γ mRNA, suggesting that they were likely to be directly regulated by IFN-γ in an autocrine manner." (PMID 35296070, 2022). "It is induced by Influenza infection and elevates ISGylation as an ISG15 E3 ligase." (PMID 31665046, 2019). "Reduction of STING gene expression or other anti-viral factors (e.g. IFNB1, MX1, ISG15) by apocynin, may in part, explain the slight increase in influenza gene transcription following apocynin treatment." (PMID 30341336, 2018). "Mice lacking ISG15 expression were more susceptible to influenza, sindbis and herpes simplex viruses." (PMID 27626177, 2016). "Mice lacking ISG15 have increased susceptibility to influenza, herpes virus type 1, and Sindbis virus infection." (PMID 21533103, 2011). "ISG15 knock-out mice proved to be more sensitive to Influenza, Herpes and Sindbis viral infection." (PMID 18560560, 2008). "In such a situation, ISGs such as IRF7, MX1 and ISG15 are unable to elicit antiviral effects against some severe influenza strains resistant to these genes, while IFTIM can elicit antiviral effects and circumvent fatal events associated with severe influenza pandemic viruses." (PMID 38932312, 2024). "On the other hand, influenza H1N1 and H3N2 (OK/483) infections significantly elevated the IFN-λ1, IFN-λ2/3, IP-10, ISG15, and MDA5 mRNA levels compared with the mock infection." (PMID 40431161, 2025). "Both ISG15 and IFIT1 are exemplars of well-described ISGs with known antiviral functionality in the setting of SARS-CoV-2, HCMV, and influenza infections." (PMID 40815167, 2025). "Role of Hypercytokinemia/hyperchemokinemia in the Pathogenesis of Influenza pathway was found to be significantly upregulated in the severe group’s monocytes with DEGs of AREG, CCL3, CCL4, CXCL8, IL1B, and ISG15 (coverage = 7% and p < 0.001)." (PMID 37495649, 2023).
influenza (continued). "IFN-stimulated genes (ISG) were also broadly upregulated in lethal disease, including canonical ISGs and genes that have been shown to be important in restricting influenza infection, such as MX1, ISG15 and IFITM1." (PMID 35271686, 2022). "While ISG15 did not exhibit significant changes in expression in this dataset, it has been well-documented as an interferon-induced antiviral gene during influenza infection." (PMID 41404797, 2025). "In the Influenza test, only the gene ISG15 did not manifest a notable distinction between the group with the disease and those in good health, while the remaining 21 genes exhibited substantial disparities." (PMID 38601162, 2024). "They determined that while the infection of cells at a high MOI with various influenza B viral strains upregulated free ISG15, no ISG15 conjugates were detected." (PMID 21994614, 2010). "SCoV2/D614G infection induced the mRNA levels of IFN-β, IFN-λs, IL-8, IP-10, ISG15, MDA5, and TNF-α compared with the mock infection, where the induction of interferons (IFN-β, IFN-λ1, and IFN-λ2/3) and MDA5 were greater than that of the influenza H1N1 and H3N2 infections." (PMID 40431161, 2025). "The expression of interferon response genes STAT1, STAT2, Mx1, OASL2, ISG15, chemokines CCL2, CCL3, CXCL9 and CXCL10, and the frequency of neutrophils (CD45+CD11b+Ly6G+) and CD4+ T cells (CD45+CD4+) were all significantly increased in influenza-infected mice when compared to vehicle controls." (PMID 38750107, 2024). "Although infection by influenza and Zika (ZIKV) viruses has been shown to increase ISGylation, SARS-CoV-2 PLpro mediates the de-ISGylation of ISGylated proteins, increasing the level of free (unconjugated) ISG15 in macrophages, which increases the ratio of free ISG15 to the conjugated ISG15." (PMID 35631059, 2022). "Whilst influenza infection increased the production of pro-inflammatory cytokines and chemokines, as with RSV infection, treatment with vitamin D either before or after influenza infection decreased gene expression of TNF-α, IFN-β, ISG15, CXCL8, IL-6 and RANTES (CCL5)." (PMID 26035247, 2015).